NEIL3 (nei like DNA glycosylase 3)
Description:
DNA glycosylase which prefers single-stranded DNA (ssDNA), or partially ssDNA structures such as bubble and fork structures, to double-stranded DNA (dsDNA). Mediates interstrand cross-link repair in response to replication stress: acts by mediating DNA glycosylase activity, cleaving one of the two N-glycosyl bonds comprising the interstrand cross-link, which avoids the formation of a double-strand break but generates an abasic site that is bypassed by translesion synthesis polymerases (By similarity). In vitro, displays strong glycosylase activity towards the hydantoin lesions spiroiminodihydantoin (Sp) and guanidinohydantoin (Gh) in both ssDNA and dsDNA; also recognizes FapyA, FapyG, 5-OHU, 5-OHC, 5-OHMH, Tg and 8-oxoA lesions in ssDNA. No activity on 8-oxoG detected. Also shows weak DNA-(apurinic or apyrimidinic site) lyase activity. In vivo, appears to be the primary enzyme involved in removing Sp and Gh from ssDNA in neonatal tissues.
Synonyms: FLJ10858; hFPG2; FPG2; hNEI3; ZGRF3; FGP2; NEI3
Tractability: PROTAC: ubiquitination databases record sites on it.
Gene: Protein-coding gene on chromosome 4 (177,309,860 to 177,362,936, forward strand). Ensembl gene ENSG00000109674.
Subcellular location: Nucleus; Chromosome
Subcellular location (Human Protein Atlas): Nucleoplasm
Pathways (Reactome):
DNA Repair: Cleavage of the damaged purine; Cleavage of the damaged pyrimidine; NEIL3-mediated resolution of ICLs; Recognition and association of DNA glycosylase with site containing an affected purine; Recognition and association of DNA glycosylase with site containing an affected pyrimidine
Disease: Defective Base Excision Repair Associated with NEIL3
Gene Ontology:
Molecular function: class I DNA-(apurinic or apyrimidinic site) endonuclease activity; DNA N-glycosylase activity; DNA-(apurinic or apyrimidinic site) endonuclease activity; single-stranded DNA binding; bubble DNA binding; damaged DNA binding; double-stranded DNA binding; MCM complex binding; DNA binding; hydrolase activity, hydrolyzing N-glycosyl compounds; nucleic acid binding; zinc ion binding
Biological process: base-excision repair; single strand break repair; base-excision repair, AP site formation; depurination; interstrand cross-link repair; DNA repair
Cellular component: nucleoplasm; nucleus; chromosome
Genetic constraint (gnomAD): Loss-of-function variants: 41 observed, 50.61 expected, observed/expected ratio (o/e) 0.81, 90% interval 0.63 to 1.05. The upper end of that interval is the gene's LOEUF score, 1.05, which puts it in group 4 of 6, group 1 being the genes least tolerant of losing a copy. Missense variants: 678 observed, 721.81 expected, observed/expected ratio (o/e) 0.94, 90% interval 0.88 to 1. Synonymous variants: 251 observed, 251.45 expected, observed/expected ratio (o/e) 1, 90% interval 0.9 to 1.11.
Gene-disease validity (ClinGen):
ClinGen rates the evidence that NEIL3 causes each of these diseases.
autoimmune disease (autosomal recessive): Disputed. A disorder resulting from loss of function or tissue destruction of an organ or multiple organs, arising from humoral or cellular immune responses of the individual to their own tissue constituents.
Homologues: Orthologues: chimpanzee NEIL3 (92% identical), macaque NEIL3 (92% identical), rabbit NEIL3 (80% identical), guinea pig NEIL3 (79% identical), dog NEIL3 (78% identical), pig NEIL3 (78% identical), mouse Neil3 (74% identical), rat Neil3 (73% identical), tropical clawed frog neil3 (52% identical), zebrafish neil3 (51% identical). Paralogues in human: NEIL2 (12% identical), NEIL1 (11% identical).
Diseases named in the same sentence as NEIL3 in open-access papers:
NEIL3 is named in the same sentence as 68 diseases in open-access papers, as found by Europe PMC text mining. Sharing a sentence is not in itself a finding about the gene and the disease. The quoted sentences say what the papers report.
prostate carcinoma (11 papers, 2011 to 2025). A carcinoma that arises from epithelial cells of the prostate gland. "Although the underlying mechanism is still uncovered, NEIL3 can be considered a novel biomarker and potential therapy target for prostate cancer." (PMID 35392496, 2022). "What's more, the variation of NEIL3 was found out to increase pesticide-associated prostate cancer risk after replication." (PMID 35392496, 2022). "A recent study demonstrated that deficiency of NEIL3 contributes to chemoresistance through modulating DNA damage repair in prostate cancer, suggesting the potential clinical and therapeutic application of NEIL3." (PMID 34659404, 2021). "Here, we found that loss of NEIL3 activated radiotherapy resistance in the progression of prostate cancer potentially via the ATR/CHK1 pathway." (PMID 34591415, 2021). "It has been reported that the loss of NEIL3 in prostate cancer could inhibit cell apoptosis and cell cycle arrest under cisplatin treatment." (PMID 35656315, 2022). "In addition, a recent study discovered that the loss of NEIL3 promotes chemotherapy resistance in prostate cancer, further proving our result from the opposite side." (PMID 36612106, 2022). "Interestingly, NEIL3, although also overexpressed in gastric, colorectal and prostate cancers and promoting their progression, was associated with a good prognosis." (PMID 36497204, 2022). "The frequent mutation in NEIL3 in prostate cancer was also detected in Caucasians." (PMID 35392496, 2022). "In summary, the loss of NEIL3 promotes chemotherapy resistance in prostate cancer, and NEIL3 may serve as a diagnostic marker for chemotherapy-resistant patients." (PMID 33921035, 2021). "Specifically, NEIL3 SNPs were associated with the risk of glioma, prostate, and thyroid cancer, with rs7689099 being associated with a reduced risk of differentiated thyroid carcinoma and prostate cancer." (PMID 30591675, 2018). "Supporting our NEIL3 interaction finding, fonofos has previously been associated with prostate cancer in the AHS among participants with a family history of prostate cancer, which suggested a role of genetic susceptibility to carcinogenic effects of this chemical." (PMID 21810555, 2011). "Interestingly, NEIL3 was barely expressed in the tissues or cells of CRPC, NEPC and chemoresistant-prostate cancer, suggesting that NEIL3 may be associated with developing prostate cancer resistance." (PMID 36497204, 2022). "The spatial transcriptome sequencing results acquired from SpatialDB showed the location of FOXM1 and NEIL3 expressions in prostate cancer." (PMID 35392496, 2022). "The results indicate that NEIL3 was little expressed in docetaxel-resistant prostate cancer clinical samples and cell lines." (PMID 33921035, 2021). "To validate this hypothesis, we examined the expression levels of NEIL3 in docetaxel-resistant prostate cancer (GSE51005 and GSE158494)." (PMID 33921035, 2021). "Therefore, the therapeutic modality of radiotherapy or chemotherapy combined with NEIL3 inducers may hold some promise in the therapeutic study of prostate cancer." (PMID 36497204, 2022). "The cell therapy models showed that the loss of NEIL3 could promote the chemotherapy resistance (but not ADT resistance) of prostate cancer (PCa)." (PMID 33921035, 2021). "In the cancer cell models that received radiotherapy or chemotherapy (nzarotamide, docetaxel and cisplatin), NEIL3 knockdown significantly reduced the sensitivity of prostate cancer cells to radiotherapy or chemotherapy but did not affect ADT resistance." (PMID 36497204, 2022). "Taken together, we believe that NEIL3 improved the prognosis of prostate cancer, but did not directly affect its proliferation or metastasis." (PMID 34591415, 2021). "However, only NEIL3, CEP55, and DEPDC1B had a significant relationship with the prognosis of prostate cancer." (PMID 34591415, 2021).
prostate carcinoma (continued). "To verify the role of NEIL3 in therapeutic sensitivity, we constructed NEIL3 knockdown cell lines via transfecting two small interfering RNAs into lymph node carcinoma of the prostate (LNcap), Duke University 145 (DU145) and prostate cancer cell line (PC3) cells." (PMID 33921035, 2021).
hepatocellular carcinoma (10 papers, 2020 to 2025). A malignant tumor that arises from hepatocytes. "A study has found that NEIL3 can prevent senescence in hepatocellular carcinoma by repairing oxidative damage to telomeres during mitosis, and it is associated with poor prognosis." (PMID 36816967, 2023). "Previous research has confirmed that NEIL3 has a crucial role in DNA repair, and it is related to adverse outcomes of several tumors, including hepatoma, lung cancer, and melanoma." (PMID 36816967, 2023). "NEIL3 can repair Oxidative Lesions at Telomeres during Mitosis in order to avert Senescence in Hepatocellular Carcinoma." (PMID 36158697, 2022). "EMT in hepatoma may be promoted by NEIL3 through activation of the BRAF/MEK/ERK/TWIST signaling pathway." (PMID 40761744, 2025). "In hepatocellular carcinoma (HCC), NEIL3 repairs oxidative damage to telomeres and prevents telomere shortening during mitosis." (PMID 40761744, 2025). "However, there are few studies on the role of NEIL3 in hepatocellular carcinoma (HCC)." (PMID 34659404, 2021). "NEIL3 may be a latent tumor suppressor gene for hepatocellular carcinoma." (PMID 32631357, 2020). "For instance, in hepatocellular carcinoma (HCC), SNHG3 regulates NEIL3 expression through transcription factor E2F1, implicating it as a potential diagnostic marker and therapeutic target." (PMID 39349640, 2024). "According to a previous study, NEIL3 elevated the expression of EMT factors, including the E/N-cadherin switch and the transcription of MMP genes, and promoted the invasion, migration, and stemness phenotypes in hepatocellular carcinoma cells." (PMID 36612106, 2022). "The expression of NEIL3 and NT5DC2 was not obvious in hepatocellular carcinoma cells." (PMID 37745297, 2023).
atherosclerosis (7 papers, 2016 to 2025). A disease characterized by the build-up of fatty material and calcium deposition in the arterial wall resulting in partial or complete occlusion of the arterial lumen. "This phenomenon is associated with increased activation of the Akt signaling pathway, which promotes atherosclerosis through Akt-dependent proliferation in NEIL3-deficient VSMCs81." (PMID 40033009, 2025). "Atherosclerosis progression is accelerated in NEIL3-deficient individuals via activation of the Akt signaling pathway and other non-canonical processes impacting the phenotype of vascular smooth muscle cells." (PMID 38275601, 2023). "We have previously shown that Apoe−/−Neil3−/− mice develop more atherosclerosis than Apoe−/− mice in an age-dependent manner, suggesting a potential role for Neil3 in accelerated aging that predisposes to enhanced atherogenesis." (PMID 35079641, 2022). "Herein, we explored the role of NEIL3 in telomere maintenance in vivo by studying bone marrow cells from atherosclerosis-prone NEIL3-deficient mice." (PMID 35079641, 2022). "The connection between NEIL3 and gut microbiota and its association with atherosclerosis in humans, however, need further investigation." (PMID 34611194, 2021). "We suggest that these metabolic alterations serve as drivers of atherosclerosis in NEIL3-deficient mice." (PMID 34611194, 2021). "The 16-week-old mice were therefore chosen for further experiments to elucidate the underlying mechanisms of NEIL3-deficiency-driven atherosclerosis." (PMID 34611194, 2021). "We have previously shown that NEIL3-deficient mice develop more atherosclerosis than control mice at a mature age8,9." (PMID 34611194, 2021). "To elucidate the potential role of enhanced NEIL3 expression in human carotid plaques, we examined the effect of Neil3 deficiency in experimental atherosclerosis." (PMID 27328939, 2016). "We hypothesize that NEIL3 functions as a telomere-protecting protein in bone marrow and that loss of NEIL3 leads to increased risk of age-related disease such as atherosclerosis." (PMID 35079641, 2022). "Increased plasma LPS in the NEIL3-deficient mice further suggests a link between our observations in the gut of the mice and development of atherosclerosis, as the NEIL3-deficient mice develop extensive atherosclerosis with age." (PMID 34611194, 2021). "Here, this hypothesis was investigated by several experimental approaches, including examination of samples from patients with carotid atherosclerosis, studies of Neil3 deficiency in atherosclerosis-prone mice and in vitro experiments in relevant cell lines." (PMID 27328939, 2016). "Studies suggested that deficiency of the BER pathway may accelerate atherosclerosis formation, and NEIL3 was shown to have increased expression in human atheromatous plaques and may play a role in inhibiting atherosclerosis formation, but whether it relies on DNA repair capacity is unclear." (PMID 36497204, 2022). "In summary, our results reveal a novel role for murine Neil3 in balancing lipid metabolism that involves effects on hepatic lipid metabolism as well as cholesterol efflux capacity in macrophages, resulting in accelerated atherosclerosis in Neil3 deficient mice on an Apoe−/− background." (PMID 27328939, 2016). "NEIL3 not only hydrolyzes glycosidic bonds but also affects lipid metabolism, contributing to the prevention of atherosclerosis." (PMID 40033009, 2025). "Aim to clarify the specific function of DNA glycolase Neil3 in the development of atherosclerosis, specifically in regard to vascular smooth muscle cell phenotypic modulation." (PMID 35419441, 2022). "A series of studies have confirmed that Neil3-/- would probably lead to decreased bone marrow hematopoietic capacity, autoimmune defects, cardiovascular disease (atherosclerosis, myocardial infarction, myocardial rupture) and neurological disorders." (PMID 36497204, 2022).
atherosclerosis (continued). "In this study we explore the metabolic events preceding development of extensive atherosclerosis in Apoe−/−Neil3−/− and Apoe−/− mice to further map the role of NEIL3 in atherogenesis." (PMID 34611194, 2021). "Despite these backup activities, our results indicate that Neil3 is indispensable to avoid increased atherosclerosis in mice on an Apoe−/− background." (PMID 27328939, 2016). "We first examined if NEIL3 gene expression was regulated in clinical atherosclerosis by assessing transcript levels in human carotid plaques of two different study populations (i.e., Biobank of Karolinska Endarterectomies [BiKE] of Stockholm 10 and Biobank of Oslo)." (PMID 27328939, 2016). "Here, we examined the role of murine Neil3 in mice prone to develop atherosclerosis." (PMID 27328939, 2016). "Hence, studies in a mouse model overexpressing Neil3 may provide valuable insight into the role of Neil3 in human atherosclerosis." (PMID 27328939, 2016). "Based on NEIL3′s role in repair of oxidative DNA damage and its impact on cell proliferation and regeneration following ischemic injury, we hypothesized that NEIL3 could play a role in diseases characterized by metabolic and oxidative stress such as atherosclerosis." (PMID 27328939, 2016).
Autoimmunity (7 papers, 2017 to 2025). The occurrence of an immune reaction against the organism's own cells or tissues. "Neil3−/− mice exhibit increased apoptosis of splenic T and B cells, indicating an increased risk for autoimmunity due to the release of self-antigens." (PMID 40033009, 2025). "NEIL3 deficiency is associated with increased lymphocyte apoptosis, autoantibody production and a predisposition toward autoimmunity." (PMID 40033009, 2025). "Concordantly, NEIL3 deficient patients developed severe autoimmunity and suffered from fatal recurrent infections." (PMID 32547565, 2020). "A recent study postulated a possible role of the base excision repair enzyme Nei endonuclease VIII-like 3 (NEIL3) deficiency as an additional factor contributing to autoimmunity in the presence of LRBA deficiency." (PMID 28197149, 2017). "Similarly, reduced expression of the excision repair enzyme NEIL3, which was previously established as a driver of autoimmunity predisposition, was also associated with loss of renal function." (PMID 39135941, 2024). "As mentioned in the literature review, NEIL3 plays a crucial role in preventing autoimmunity and cell proliferation." (PMID 33879165, 2021). "Some findings based on a Neil3−/− mice model indicated that the NEIL3 mutation was linked to impaired B cell function and severe autoimmunity." (PMID 33879165, 2021). "They tested this “double-hit hypothesis;” they generated Neil3-deficient mice, which, like their human counterparts, displayed no overt signs of autoimmunity until faced with a second environmental challenge, suggesting that environmental effects can potentiate a genotype." (PMID 41608500, 2025).
breast cancer (7 papers, 2021 to 2025). A primary or metastatic malignant neoplasm involving the breast. "NEIL3 overexpression was significantly associated with different stages of tumor progression in breast cancer and poor prognosis in triple-negative breast cancer patients versus non-triple-negative breast cancer." (PMID 36233194, 2022). "Although the expression of NEIL3 and the poor prognosis of the overall population of breast cancer lack statistical support, NEIL3’s low expression patients show bad prognoses trend in ER-negative patients and have statistical differences (p < 0.05)." (PMID 36233194, 2022). "The cancer-promoting effects of NEIL3 have been proven in multiple cancers, including prostate, liver, and breast cancers." (PMID 35535347, 2022). "The transcription of NEIL3 as a cell cycle dependent gene is regulated by BRG1 in breast cancer cells." (PMID 33879165, 2021). "The BRG1-EP300 complex drives NEIL3 transcription in breast cancer." (PMID 40761744, 2025). "NEIL2 and NEIL3 play a role in the development and progression of breast cancer." (PMID 40761744, 2025). "NEIL3 may also be involved in the tumorigenesis induced by estrogen and progestin therapy in breast cancer." (PMID 40761744, 2025). "In conclusion, NEIL2 may provide new perspectives for breast cancer treatment, and NEIL3 may have a role in the onset and progression of breast cancer." (PMID 40761744, 2025). "We acquired the ChIP-seq data of FOXM1 targeting NEIL3 in breast cancer from Cistrome Data Browser." (PMID 35392496, 2022). "In conclusion, the current study showed that CCNE2, CDCA5, RAD51, TCF19, KNTC1, MCM10, and NEIL3 might contribute to EPT-related tumorigenesis in breast cancer, with CCNE2 might be a sensitive risk indicator of breast cancer risk in women using MHT." (PMID 36233194, 2022). "In all breast cancer, low expression of NEIL3, CDC25C and NEK2 predicted high RFS (p < 0.05) respectively, while high expression of HCN2 predicted high RFS (p < 0.05), and low expression of NEIL3, CDC25C, NEK2 and HCN2 predicted high OS respectively (p < 0.05)." (PMID 33644115, 2021). "In addition, some studies indicated NEIL3 as a cell cycle dependent gene was regulated by BRG1 in breast cancer cells and that NEIL3 overexpression may facilitate distant metastasis in primary melanoma." (PMID 33879165, 2021). "Here, we found that low expression of NEIL3, CDC25C, and NEK2 predicted high RFS and OS respectively (p < 0.05), and low expression of HCN2 predicted high OS (p < 0.05) in all breast cancer." (PMID 33644115, 2021). "These analytical data suggest that NEK2 may be involved in the recurrence of Basal-, LumA- and LumB-subtype breast cancer, while NEIL3 and CDC25C may only be involved in recurrence of LumA-subtype breast cancer." (PMID 33644115, 2021). "According to the existing literature, except for NEK2 the expression and prognostic significance of the NEIL3, CDC25C, and HCN2 genes are still unknown in breast cancer." (PMID 33644115, 2021).